PSMC2 (proteasome 26S subunit, ATPase 2)
Diseases named in the same sentence as PSMC2 in open-access papers (continued):
Sharing a sentence is not in itself a finding about the gene and the disease.
gastric cancer (4 papers, 2022 to 2023). A primary or metastatic malignant neoplasm involving the stomach. "Our study obtained similar results, suggesting that the high expression of PSMC2 was associated with the low overall survival of gastric cancer patients." (PMID 35256584, 2022). "Overexpression of RPS15A promoted the proliferation and migration of gastric cancer cells, which alleviated the inhibitory effect caused by PSMC2 knockdown to a certain extent." (PMID 35256584, 2022). "The same studies reported tumor growth limiting activity upon PSMC2 knockdown in mouse prostate, breast, and gastric cancer models." (PMID 37529110, 2023). "In summary, both PSMC2 and RPS15A were significantly overexpressed in gastric cancer, and PSMC2 upregulated RPS15A by inhibiting the expression of hsa-let-7c-3p." (PMID 35256584, 2022). "The analysis results of Sign test indicated that the expression of PSMC2 was statistically different in gastric cancer and para-carcinoma tissues." (PMID 35256584, 2022). "For the purpose of investigating the role of PSMC2 in gastric cancer, three shPSMC2 lentiviruses (shPSMC2-1, shPSMC2-2 shPSMC2-3) were designed and infected in the MGC-803 cells." (PMID 35256584, 2022). "We will focus on the function and mechanism of PSMC2 in the progression of gastric cancer, and further verify it at the cellular and animal levels." (PMID 35256584, 2022). "We used TargetScan and TCGA databases to predict 7 downregulated miRNAs in gastric cancer that not only bound to PSMC2 but also targeted RPS15A." (PMID 35256584, 2022). "Further cell function tests revealed that downregulation of PSMC2 inhibited the proliferation, clone formation and migration of gastric cancer cells, and enhanced apoptosis." (PMID 35256584, 2022). "A recent study found that PSMC2 promotes gastric cancer progression by targeting hsa-let-7c-3p to increase the level of RPS15A, which then activates the mTOR pathway." (PMID 36110217, 2022). "The results of immunohistochemical staining determined that PSMC2 was highly expressed in the gastric cancer tissues." (PMID 35256584, 2022). "In this study, the levels of PSMC2 in gastric cancer tissues were significantly higher than that in para-carcinoma tissues, and the expression of PSMC2 was positively correlated with pathological stage, Tumor Infiltrate, and Ki67 expression." (PMID 35256584, 2022). "Through bioinformatic analysis of the sequencing results of PSMC2 knockdown gastric cancer cells, it was found that PSMC2 overexpression upregulated ribosomal protein S15A (RPS15A) at the transcription and translation levels." (PMID 35256584, 2022). "Further statistical analysis suggested that the expression of PSMC2 in gastric cancer patients showed statistically differences in tumor characteristic such as pathological stage, Tumor Infiltrate, Ki67 expression and age." (PMID 35256584, 2022). "Inhibition of hsa-let-7c-3p promoted the migration of MGC-803 cells and reduced the apoptosis level, while simultaneous inhibition PSMC2 and hsa-let-7c-3p restored the migration and apoptosis levels of gastric cancer cells." (PMID 35256584, 2022). "According to Kaplan–Meier survival analysis results, PSMC2 expression was significantly correlated with overall survival of gastric cancer patients, that was, the high expression of PSMC2 indicated a poor prognosis." (PMID 35256584, 2022). "Cell function experiments indicated that PSMC2 knockdown inhibited the proliferation, clone formation and migration of gastric cancer cells, and induced apoptosis." (PMID 35256584, 2022). "All of these results suggested that PSMC2 might play a vital role in the development and prognosis of gastric cancer." (PMID 35256584, 2022). "This revealed that overexpression of PSMC2 upregulated the expression of RPS15A in gastric cancer." (PMID 35256584, 2022). "Consequently, PSMC2 promoted the proliferation and migration of gastric cancer cells by upregulating RPS15A." (PMID 35256584, 2022).
gastric cancer (continued). "The results of immunohistochemical staining showed that PSMC2 was upregulated in gastric cancer." (PMID 35256584, 2022). "In this study, we found that PSMC2 was significantly highly expressed in gastric cancer tissues, and its expression in patients with gastric cancer was correlated with tumor characteristic such as pathological stage, T Infiltrate, the expression of Ki67 and age." (PMID 35256584, 2022). "However, there are still some deficiencies in this study, that is, more clinical samples are needed to detect the expression of hsa-let-7c-3p in gastric cancer, and to verify the correlation between PSMC2, hsa-let-7c-3p and RPS15A." (PMID 35256584, 2022). "Hence, PSMC2 downregulation inhibited the progression of gastric cancer." (PMID 35256584, 2022). "Therefore, we further explored the effect of PSMC2/RPS15A/mTOR pathway on gastric cancer." (PMID 35256584, 2022). "In addition, we also confirmed that the promoting effect of PSMC2/RPS15A on gastric cancer progression, suggesting that PSMC2/RPS15A may be potential targets for targeted therapy of gastric cancer." (PMID 35256584, 2022). "Gastric cancer cells (AGS and MGC-803 cells) with RPS15A overexpression or RPS15A overexpression and PSMC2 knockdown were constructed in vitro." (PMID 35256584, 2022). "In summary, PSMC2 activated mTOR pathway through upregulation of RPS15A, thus promoting the progression of gastric cancer." (PMID 35256584, 2022). "Knockdown of RPS15A decreased the proliferation and migration ability of gastric cancer cells, whereas overexpression of RPS15A alleviated the inhibition of PSMC2 knockdown on the proliferation and migration." (PMID 35256584, 2022). "PSMC2 enhanced RPS15A levels by targeting hsa-let-7c-3p, and then activated mTOR pathway, thereby promoting the progression of gastric cancer." (PMID 35256584, 2022). "In conclusion, PSMC2 and RPS15A were highly expressed in gastric cancer." (PMID 35256584, 2022). "However, the functional verification and mechanism research inhibition of PSMC2 in the progression of gastric cancer are lacking." (PMID 35256584, 2022). "Besides, IPA results showed an interaction between PSMC2 and RPS15A/mTOR pathway, suggesting that PSMC2 might be involved in the progression of gastric cancer through RPS15A/mTOR pathway." (PMID 35256584, 2022). "However, the role and mechanism of PSMC2 regulating mTOR pathway through RPS15A in gastric cancer was not reported." (PMID 35256584, 2022).
breast carcinoma (3 papers, 2021 to 2022). "Herein, we showed that PSMC2 is overexpressed in human breast cancer and is associated with advanced tumor grade." (PMID 34244472, 2021). "However, till now, the biological function of PSMC2 in human breast cancer and the underlying mechanism were still unclear." (PMID 34244472, 2021). "In order to investigate the PSMC2 expression level in breast cancer specimens, a breast cancer tissue microarray consisting of 173 breast cancer samples and 35 para-carcinoma samples was used for IHC staining." (PMID 34244472, 2021). "The results of our study verified the high expression of PSMC2 in human breast cancer and the promotion effects of PSMC2 on its development and progression." (PMID 34244472, 2021). "The results revealed that lower expression of PSMC2 in breast cancer cells markedly induced apoptosis compared with shCtrl cells." (PMID 34244472, 2021). "Using complementary molecular approaches in multiple cellular models in vivo and in vitro, we demonstrated that PSMC2 plays an important role in tumorigenesis and the development of breast cancer through the regulation of PLAU signaling." (PMID 34244472, 2021). "More importantly, the in vivo study using mice xenograft model strongly supported the critical role of PSMC2 expression in breast cancer development." (PMID 34244472, 2021). "Our results indicated that breast cancer cells with comparatively low PSMC2 expression showed slower proliferation rate and weaker colony formation ability, with relatively higher apoptosis rate." (PMID 34244472, 2021). "Compared to para-cancer tissues, PSMC2 level was considerably elevated in breast cancer, which was significantly correlated with tumor grade." (PMID 34244472, 2021). "In this study, we found that PSMC2 expression possesses a significant relationship with the grade and age of breast cancer." (PMID 34244472, 2021). "The mechanistic research revealed that PSMC2 promotes the development and progression of human breast cancer through interacting with PLAU." (PMID 34244472, 2021). "To further verify this issue, we used flow cytometry to analyze cell apoptosis and cell cycle distribution in PSMC2 silenced breast cancer cells." (PMID 34244472, 2021). "Outcomes of our study showed that overexpression of PSMC2 provide tumorigenic and metastatic advantages in breast cancer, which may involve the regulation of PLAU." (PMID 34244472, 2021). "To determine the importance of PSMC2 in breast cancer development, we silenced PSMC2 via lentivirus-mediated transferring of short hairpin RNAs (shRNAs) into two human breast cancer cell lines (MCF-7, MDA-MB-231), which expressed significantly higher PSMC2 than mammary epithelial cell line HBL-100." (PMID 34244472, 2021). "Moreover, we investigated the functions of PSMC2 in breast cancer cell proliferation, apoptosis, colony formation, migration, invasion and tumorigenesis via loss-of-functional studies." (PMID 34244472, 2021). "For the sake of further exploring whether PLAU mediated the functions of PSMC2 in breast cancer, lentivirus expressing shPLAU was prepared for infecting MDA-MB-231 cells alone or together with shPSMC2." (PMID 34244472, 2021). "Notably, PSMC2 expression presented a positive correlation with the pathological grade of breast cancer." (PMID 34244472, 2021). "Knockdown or overexpression of PLAU could enhance or alleviate the inhibition of PSMC2 depletion on breast cancer development." (PMID 34244472, 2021). "Through the detection of tissue microarray, we found the overexpression of PSMC2 breast cancer." (PMID 34244472, 2021). "In summary, these results revealed that high levels of PSMC2 expression might be related to breast cancer development and may serve as a prognostic biomarker." (PMID 34244472, 2021). "Therefore, herein, the cooperative effects of PLAU and PSMC2 on the development and progression of breast cancer were illustrated." (PMID 34244472, 2021).
breast carcinoma (continued). "Taken together, PSMC2 could potently facilitate tumorigenesis and metastasis in many respects throughout the progression of breast cancer." (PMID 34244472, 2021). "Knockdown of PSMC2 suppressed breast cancer progression in vitro and in vivo." (PMID 34244472, 2021). "Moreover, we analyzed the relationship between PSMC2 expression level and tumor characteristics in patients with breast cancer." (PMID 34244472, 2021). "Both mRNA and protein levels of PSMC2, PSMC3, PSMC4, PSMC5, and PSMC6 were significant in cancer tissues, and PSMC1, PSMC3, PSMC4, PSMC5, and PSMC6 overexpression was associated with poor prognoses of breast cancer patients." (PMID 34329194, 2021). "Moreover, knockdown of PSMC2 also was able to inhibit the motility of breast cancer cells, suggesting its role in tumor metastasis, which is also an important property of malignancy." (PMID 34244472, 2021). "Therefore, we sought to establish a correlation between breast cancer and PSMC2." (PMID 34244472, 2021). "Collectively, we deduced that PSMC2 may regulate breast cancer through PLAU." (PMID 34244472, 2021). "The present findings showed significantly higher expression profiles of PSMC2, PSMC3, PSMC4, PSMC5, and PSMC6 in breast cancer compared to normal breast tissues." (PMID 34329194, 2021). "The data demonstrated that PSMC1-6 presented moderate protein expressions, and PSMC2, PSMC3, and PSMC5 were highly expressed in certain clinical tissues from breast cancer specimens." (PMID 34329194, 2021). "Consequently, as with PLAU, PSMC2 may be a viable therapeutic target in breast cancer." (PMID 34244472, 2021). "Our results showed that PSMC2/PLAU axis promoted the tumorigenesis and development of breast cancer." (PMID 34244472, 2021). "Given the link between PSMC2 and PLAU, we next determined the mechanism of PLAU upregulation by PSMC2 in breast cancer." (PMID 34244472, 2021). "According to our results from an Oncomine analysis of mRNA expressions of PSMC2, PSMC3, PSMC4, PSMC5, and PSMC6, these members are highly upregulated in breast cancer tissues; therefore, we chose breast cancer to perform further bioinformatics analyses." (PMID 34329194, 2021). "We recognized a positive correlation between PSMC2 and PLAU, which plays a crucial role in the metastatic process of breast cancer." (PMID 34244472, 2021). "Indeed, PSMC2, PSMC3, PSMC4, PSMC5, and PSMC6 were recently reported as highly expressed in breast cancer, which correlated with worse outcomes." (PMID 36498916, 2022). "More importantly, cell lines with mere PSMC2 knockdown (shPSMC2+Vector), mere PLAU overexpression (PLAU + shCtrl), or simultaneous PSMC2 knockdown and PLAU overexpression (shPSMC2+PLAU) were constructed for further demonstrating the synergistic effects of PSMC2 and PLAU on breast cancer development." (PMID 34244472, 2021).
diabetes (3 papers, 2015 to 2019). "It is likely that the difference in expression of the lymphocyte-enriched genes Psmc2, Dag1 and Tbk1 in mice with early or late diabetes onset was under-estimated by the analysis in whole blood, in which lymphocytes are under-represented." (PMID 26366287, 2015).
cancer of the prostate (2 papers, 2021 to 2022). "Albeit these results, the underlying mechanism of the regulatory effects of PSMC2 on the development and metastasis of prostate cancer is still poorly understood and would be the focus of next research." (PMID 33902600, 2021). "qPCR further detected high levels of PSMC2 expression in a range of prostate cancer cell lines (DU 145, PC-3, and C4-2) thus demonstrating the strong association between PSMC2 expression and prostate cancer." (PMID 33902600, 2021). "The results demonstrated that PSMC2 was upregulated in tumor tissues of prostate cancer and its high expression was significantly associated with advanced Gleason grade and higher Gleason score." (PMID 33902600, 2021). "As such, this study provided novel insights into PSMC2 as a potential therapeutic target for the treatment of prostate cancer." (PMID 33902600, 2021). "Collectively, these results indicated that the PSMC2 knockdown inhibits the development and progression of prostate cancer by regulating mechanisms related to cell proliferation." (PMID 33902600, 2021). "Next, we investigated the potential role of PSMC2 in the metastasis of prostate tumors and the migration of prostate cancer cells." (PMID 33902600, 2021). "It was also evident that tumors with a higher Gleason grade expressed higher levels of PSMC2, thus indicating a positive relationship between PSMC2 levels and Gleason grade in cases of prostate cancer." (PMID 33902600, 2021). "Here, expression of PSMC2 in tumor tissues or cells of prostate cancer was detected by qPCR, western blotting and immunohistochemical analysis." (PMID 33902600, 2021). "The emphasis of this study lied in a potential promotor acted by PSMC2 in the development and metastasis of prostate cancer." (PMID 33902600, 2021). "These lentiviral vectors were subsequently transfected into two prostate cancer cell lines (PC-3 and DU 145) in order to construct a cell model for the knockdown of PSMC2." (PMID 33902600, 2021). "Despite that PSMC2 is considered to be a newly discovered gene closely related to human cancer, its relationship with prostate cancer is still unclear." (PMID 33902600, 2021). "Based on our findings, we proposed that PSMC2 regulated prostate cancer cell partly by targeting Akt pathway." (PMID 33902600, 2021). "With respect to the results of wound-healing and transwell assays, the migration level of prostate cancer cells significantly decreased by PSMC2 knockdown." (PMID 33902600, 2021). "Collectively, these results clarified the potential role of PSMC2 as a tumor promoter in the development and progression of prostate cancer." (PMID 33902600, 2021). "PSMC2 (proteasome 26S subunit ATPase 2) is a key member of the 19S regulatory subunit of 26S proteasome, whose relationship with prostate cancer is rarely studied." (PMID 33902600, 2021). "Beyond that, the in vitro experiments elucidated that the limited abilities of proliferation and colony formation of prostate cancer cells were particularly pronounced due to the inhibition of PSMC2." (PMID 33902600, 2021). "Immunohistochemical (IHC) analysis was used to investigate the expression levels of PSMC2 in specimens of tumor acquired from 145 patients with prostate cancer; these data were then compared with the expression levels of PSMC2 in normal control tissues." (PMID 33902600, 2021). "This indicated the potential involvement of the Akt/Cyclin D1/CDK6 pathway in the PSMC2-induced proliferation of prostate cancer." (PMID 33902600, 2021). "In conclusion, this study was the first to verify the promotor role played by PSMC2 in development and metastasis of prostate cancer." (PMID 33902600, 2021). "Knockdown of PSMC2 gave rise to the blocked development and metastasis of prostate cancer, which was probably resulted from regulating Akt/Cyclin D1/CDK6 signalling pathway." (PMID 33902600, 2021). "The results of our study provided evidence for PSMC2 as a tumor promotor for prostate cancer." (PMID 33902600, 2021).
cancer of the prostate (continued). "Next, we aimed to investigate the specific effects of PSMC2 in cancer of the prostate." (PMID 33902600, 2021). "In this study, PSMC2 expression was enhanced in prostate cancer cell lines and tissues." (PMID 33902600, 2021). "In agreement with previous reports indicating Akt as a target for the treatment of prostate cancer, we also observed that knockdown of PSMC2 could decrease the activity of Akt pathway, especially the decline in its phosphorylation level." (PMID 33902600, 2021). "Furthermore, the inhibition of PSMC2 led to the decrease in prostate cancer cell proliferation, colony formation and cell migration, while facilitated cell apoptosis of prostate cancer cells." (PMID 33902600, 2021). "Therefore, our in vivo studies demonstrated that the depletion of PSMC2 significantly inhibited the growth of prostate cancer cells." (PMID 33902600, 2021). "In this part of the study, we investigated the mechanisms by which PSMC2 might regulate prostate cancer." (PMID 33902600, 2021). "PSMC2 expression significantly increased in prostate cancer tissues and cell lines." (PMID 33902600, 2021). "Collectively, these results indicated that PSMC2 may promote the development of prostate cancer by regulating the Akt/Cyclin D1/CDK6 pathway." (PMID 33902600, 2021). "Moreover, the involvement of PSMC2 in prostate cancer was mediated by the activity of Akt/Cyclin D1/CDK6 signaling pathway." (PMID 33902600, 2021). "Knockdown of PSMC2 could inhibited cell proliferation, colony formation and cell migration of prostate cancer cells, while promoting cell apoptosis and cell cycle arrest." (PMID 33902600, 2021). "Our experimental data might provide a strategy for targeting with the PSMC2/Akt/Cyclin D1/CDK6 signalling pathway interaction as a novel therapeutic application to treat prostate cancer patients." (PMID 33902600, 2021). "Moreover, the regulation of prostate cancer by PSMC2 may be mediated by Akt/Cyclin D1/CDK6 signaling pathway." (PMID 33902600, 2021). "Therefore, our studies suggested that PSMC2 may act as a tumor promotor in the development and progression of prostate cancer, and could be considered as a novel therapeutic target for prostate cancer treatment." (PMID 33902600, 2021). "Nevertheless, the relationship between PSMC2 and prostate cancer has not been reported and still remains unknown." (PMID 33902600, 2021).